SLC14A1 (solute carrier family 14 member 1 (Kidd blood group))
Description:
Mediates the transport of urea driven by a concentration gradient across the cell membrane of erythrocytes. Also mediates the transport of urea across the cell membrane of the renal inner medullary collecting duct which is critical to the urinary concentrating mechanism (By similarity). Facilitates water transport in erythrocytes (By similarity).
Synonyms: HUT11; JK; RACH1; UT1; UTE; HsT1341; RACH2; HUT11A; Jk(a); Jk(b); UT-B1
Tractability: Small molecule: a structure with a bound ligand is known. Antibody: UniProt places it where antibodies can reach, with high confidence; its Gene Ontology location is reachable by antibodies, with high confidence; UniProt predicts a signal peptide or a membrane-spanning region; the Human Protein Atlas places it where antibodies can reach. PROTAC: a small molecule that binds it is known.
Target class: SLC superfamily of solute carriers; Electrochemical transporter; Transporter; SLC14 family of facilitative urea transporters
Chemical probes: compound 1a [PMID: 23597791] (high quality)
Gene: Protein-coding gene on chromosome 18 (45,687,025 to 45,752,521, forward strand). Ensembl gene ENSG00000141469.
Subcellular location: Cell membrane; Basolateral cell membrane
Subcellular location (Human Protein Atlas): Plasma membrane
Pathways (Reactome):
Transport of small molecules: SLC-mediated transport of organic cations
Gene Ontology:
Molecular function: urea channel activity; urea transmembrane transporter activity; water transmembrane transporter activity
Biological process: urea transmembrane transport; amine transport; urea transport; water transport
Cellular component: plasma membrane; basolateral plasma membrane; membrane
Genetic constraint (gnomAD): Loss-of-function variants: 37 observed, 43.83 expected, observed/expected ratio (o/e) 0.84, 90% interval 0.65 to 1.11. The upper end of that interval is the gene's LOEUF score, 1.11, which puts it in group 4 of 6, group 1 being the genes least tolerant of losing a copy. Missense variants: 469 observed, 505.83 expected, observed/expected ratio (o/e) 0.93, 90% interval 0.86 to 1. Synonymous variants: 164 observed, 182.99 expected, observed/expected ratio (o/e) 0.9, 90% interval 0.79 to 1.02.
Gene-disease validity (ClinGen):
ClinGen rates the evidence that SLC14A1 causes each of these diseases.
nephrogenic diabetes insipidus (autosomal recessive): No Known Disease Relationship. Nephrogenic diabetes insipidus (NDI) is characterized by polyuria with polydipsia, recurrent bouts of fever, constipation, and acute hypernatremic dehydration after birth that may cause neurological sequelae.
Homologues: Orthologues: chimpanzee SLC14A1 (99% identical), macaque SLC14A1 (93% identical), mouse Slc14a1 (84% identical), pig SLC14A1 (83% identical), dog SLC14A1 (81% identical), rat Slc14a1 (81% identical), rabbit SLC14A1 (80% identical), guinea pig SLC14A1 (68% identical), tropical clawed frog slc14a2 (62% identical), zebrafish slc14a2 (52% identical). Paralogues in human: SLC14A2 (62% identical).
Diseases named in the same sentence as SLC14A1 in open-access papers:
SLC14A1 is named in the same sentence as 44 diseases in open-access papers, as found by Europe PMC text mining. Sharing a sentence is not in itself a finding about the gene and the disease. The quoted sentences say what the papers report.
bladder cancer (15 papers, 2016 to 2025). "Except for SNPs, other types of variants in the SLC14A1 gene and UT-B protein have also been found to be associated with the increase in bladder cancer." (PMID 41301792, 2025). "SLC14A1, a urea transporter protein, has hitherto been primarily associated with renal functions and bladder cancer." (PMID 39061061, 2024). "In existing literature, SLC14A1’s functionality has been primarily associated with urea transport and bladder cancer susceptibility, with minimal insights into its regulatory role in cellular signaling pathways." (PMID 39061061, 2024). "It has been reported that several single nucleotide polymorphisms (SNPs) within the SLC14A1 gene (such as rs1058396, rs2298720, rs11877062, and rs17674580) are strongly correlated with bladder cancer." (PMID 36934247, 2023). "So far, GWAS researches have revealed several suspicious SNPs (single nucleotide polymorphism) within the SLC14A1 gene that are strongly associated with bladder cancer, such as rs1058396, rs2298720, rs11877062 and rs17674580." (PMID 28589430, 2017). "In this study, we found that the SLC14A1 gene, which encodes urea transporter UT-B and mediates urea transport across the cell membrane, was suppressed or aberrantly expressed in bladder cancer." (PMID 28503151, 2017). "SNP variants within SLC14A1 have been associated with urinary bladder cancer risk, and identified as a potential biomarker in prostate cancer." (PMID 27732966, 2016). "Additionally, Professor Ma and his colleagues discovered that in bladder cancer, patients with a high proportion of SLC14A1+ cancer-associated fibroblast (CAF) exhibited a poorer response to neoadjuvant chemotherapy and immunotherapy." (PMID 39061061, 2024). "In bladder cancer, the chromosomal region containing the SLC14A1 gene, at 18q12.3, has been identified as a susceptibility locus for bladder cancer, and variations in the SLC14A1 gene may offer a novel etiological perspective on bladder cancer occurrence." (PMID 39061061, 2024). "Recently, a meta-analysis of genome-wide association studies of UBUCs revealed that SLC14A1-rs10775480, a variant at intron 6, is highly associated with susceptibility in bladder cancer 10, suggesting that SLC14A1 may play a causal or regulatory role." (PMID 33052246, 2020). "Furthermore, by reviewing some well-established theories regarding the carcinogenesis of bladder cancer, including several genome wide association researches, we have bridged the mechanisms of cancer development with the aberrant expression of SLC14A1." (PMID 28589430, 2017). "Solute carrier family 14 member 1 (SLC14A1) gene encodes the type-B urea transporter (UT-B) which facilitates the passive movement of urea across cell membrane, and has recently been related with human malignancies, especially for bladder cancer." (PMID 28589430, 2017). "Recently, gene analyses demonstrate that SLC14A1 (UT-B) gene mutations are associated with bladder cancer, suggesting that urea transporter UT-B may play an important role in bladder carcinogenesis." (PMID 28503151, 2017). "STING palmitoylation triggers immune escape in renal cell carcinoma, and the STING/SLC14A1 axis also mediates chemoresistance in bladder cancer." (PMID 41275427, 2025). "Nonetheless, SLC14A1+ CAF can still serve as a target for improving the treatment responsiveness of bladder cancer patients." (PMID 39061061, 2024). "Studies has reported that SLC14A1 was regard as a novel target for human urothelial cancer 48 and urinary bladder cancer." (PMID 32547322, 2020). "In conclusion, SLC14A1 gene and UT-B protein expression are significantly changed in bladder cancers." (PMID 28503151, 2017). "Herein, we discussed the SLC14A1 gene and UT-B protein properties, aiming to elucidate the expression behavior of SLC14A1 in human bladder cancer." (PMID 28589430, 2017). "There are quite a number of reports about the relationship between bladder cancer and SLC14A1." (PMID 41301792, 2025).
bladder cancer (continued). "rs1058396 is a high-risk variant in SLC14A1 [AG, GG], and it increases bladder cancer risk, particularly in never-smokers." (PMID 41301792, 2025). "Arhgap6 and Slc14a1 have not been implicated in breast cancer but have been implicated in a number of other cancers including cervical, endometrial, prostate and bladder cancer." (PMID 28423599, 2017). "In bladder cancer, SLC14A1+ CAFs produce WNT5A to confer stemness to bladder tumor cells, in turn tumor cells drive interferon production to enhance SLC14A1+ CAF differentiation." (PMID 38773979, 2024). "Mechanistic studies revealed that the SLC14A1+ subtype of CAF in bladder cancer originates from interferon-stimulated differentiation and can secrete WNT5A, thereby activating the Wnt pathway in bladder cancer cells in a paracrine manner and enhancing tumor cell stemness." (PMID 39061061, 2024).
prostate carcinoma (9 papers, 2016 to 2025). A carcinoma that arises from epithelial cells of the prostate gland. "According to a recent MR (Mendelian randomization) analysis, SLC14A1 was identified as a biomarker closely associated with immune cell infiltration of prostate cancer." (PMID 41301792, 2025). "In prostate cancer, SLC14A1 downregulation enhances CDK1/CCNB1 and mTOR pathway activity, accelerating tumorigenesis." (PMID 40746552, 2025). "Another study similarly indicated that SLC14A1 expression in malignant prostate cancer tissues was significantly low, being inversely proportional to both the clinical grade and stage." (PMID 36934247, 2023). "The expression of SLC14A1 is significantly reduced in prostate cancer cells and tissue comparing to normal prostate epithelial cell and para-cancerous tissue." (PMID 36257969, 2022). "Our study reveals that SLC14A1, ARHGEF38, NEFH, MSMB, KRT23, and KRT15 are potential diagnostic biomarkers for prostate cancer, among which MSMB may play a protective role in prostate cancer." (PMID 40260298, 2025). "However, further basic research and clinical trials are needed to further prove our point and determine the molecular pathway that how SLC14A1 can reduce BCR in prostate cancer." (PMID 36257969, 2022). "We found that the genes SLC14A1, MSMB, KRT23, and KRT15 are primarily enriched in “prostate cancer” signaling pathway." (PMID 40260298, 2025).
urothelial carcinoma (4 papers, 2020 to 2025). A malignant neoplasm derived from the transitional epithelium of the urinary tract (urinary bladder, ureter, urethra, or renal pelvis). "We for the first time report a patient diagnosed with urothelial carcinoma accompanied with split Slc14a1 gene abnormality, a crucial gene in bladder." (PMID 32703295, 2020). "Furthermore, the SLC14A1 gene is also considered a novel tumor suppressor for urothelial carcinoma, and in PCa, the downregulation of its expression promotes tumor progression by activating the CDK1/CCNB1 and mTOR pathways and is closely associated with biochemical recurrence (BCR) of PCa." (PMID 40260298, 2025). "Studies have found that HK2 expression in urothelial carcinoma and NSCLC cells is suppressed by SLC14A1." (PMID 41301792, 2025).
colorectal cancer (3 papers, 2021 to 2025). A primary or metastatic malignant neoplasm that affects the colon or rectum. "Another investigation in CRC reported that SLC14A1 as a DEG may act as a key regulator in CRC metachronous liver metastasis, with its expression level shows a significant association with both recurrence-free survival and overall survival in individuals diagnosed with colorectal cancer." (PMID 41301792, 2025).
Alzheimer disease (2 papers, 2012 to 2025). A progressive, neurodegenerative disease characterized by loss of function and death of nerve cells in several areas of the brain leading to loss of cognitive function such as memory and language. "The SLC14A1 gene exhibits altered expression in PD-affected individuals and is conjectured to be instrumental in the regulation of Aβ production and apoptosis, potentially contributing to the pathological hallmarks of Alzheimer’s disease, PD, and muscular dystrophy." (PMID 39968123, 2025).
lung carcinoma (2 papers, 2020 to 2025). "Indeed, transfection of SLC14A1 into lung cancer cell line H520 inhibited colony formation." (PMID 32103057, 2020).
Parkinson disease (2 papers, 2012 to 2018). A progressive degenerative disorder of the central nervous system characterized by loss of dopamine producing neurons in the substantia nigra and the presence of Lewy bodies in the substantia nigra and locus coeruleus. "A thorough search of the Parkinson’s Disease Database (ParkDB) has revealed that the expression of slc14a1 and mpp1 was identified in an earlier study as dysregulated in the blood of PD patients." (PMID 22952715, 2012). "SLC14A1-s correlated with Unified Parkinson’s Disease Rating Scale total and part III scores." (PMID 29896099, 2018).
renal cell carcinoma (2 papers, 2025). "Fifthly, the involvement of SLC14A1 in hypoxia-driven renal cell carcinoma progression via mitochondrial-dependent pathways implies that oxygen-targeted therapeutic approaches could potentially improve treatment outcomes for this malignancy." (PMID 41301792, 2025).
acute myeloid leukemia (1 paper, 2025). Acute myeloid leukemia (AML) is a group of neoplasms arising from precursor cells committed to the myeloid cell-line differentiation. "Additionally, Wang’s analysis in acute myeloid leukemia (AML) revealed that SLC14A1 can act as an endocytosis-related gene (ERG) and N6-methyladenosine (m6A)-related gene, affecting AML progression and metastasis." (PMID 41301792, 2025).
alcohol addiction (1 paper, 2023). "However, four genes, SERPINA3, SLC14A1, RPS6 and RPS3A, were obtained among the alcohol addiction-related differential genes." (PMID 37065902, 2023).
colon cancer (1 paper, 2025). "Secondly, c-PTIO can reduce SLC14A1 mRNA levels in CSCs, which is highly important for the exploration of new therapeutic targets for colon cancer." (PMID 41301792, 2025).
dementia (1 paper, 2023). Loss of intellectual abilities interfering with an individual's social and occupational functions. "Thus, consistent with our previous argument regarding SLC14A1 in HD, UT-B transporters in VaD and other dementias are likely to be increased to compensate for the markedly elevated brain-urea levels." (PMID 37520429, 2023).
dermatomyositis (1 paper, 2026). Dermatomyositis (DM) is a type of idiopathic inflammatory myopathy characterized by evocative skin lesions and symmetrical proximal muscle weakness. "Using LASSO regression, SVM, random forest (RF), GBM, GLM, KNN, and NNET machine learning algorithms, four core genes were identified: SAA1, NACAD, SLC14A1, and MYBPH, all of which were highly expressed in dermatomyositis lesion tissues." (PMID 41911226, 2026).
kidney failure (1 paper, 2022). An acute or chronic condition that is characterized by the inability of the kidneys to adequately filter the blood. "AQP3 and UT-B (SLC14A1) gene expression was evaluated using RT-qPCR analysis in 76 HD patients and 35 participants with no kidney failure." (PMID 36038817, 2022).
lung adenocarcinoma (1 paper, 2023). A carcinoma that arises from the lung and is characterized by the presence of malignant glandular epithelial cells. "It was recently reported that the SLC14A1 gene is associated with human malignancies, exhibiting downregulated expression in lung adenocarcinoma specimens, while its elevated expression was found to inhibit lung squamous cell carcinoma colony formation." (PMID 36934247, 2023).
lymphoma (1 paper, 2021). A malignant (clonal) proliferation of B- lymphocytes or T- lymphocytes which involves the lymph nodes, bone marrow and/or extranodal sites. "Of the 579 overrepresented proteins, six proteins were found in at least 20-fold higher abundance in lymphoma patients (NUCKS1, SLC14A1, GPALPP1, ADPRH, CD72, PRDM15)." (PMID 33562532, 2021).
metastasis (1 paper, 2024). The spread or migration of cancer cells from one part of the body (where they first appeared) to another. "Moreover, both the analysis of CRC patients in the database and the examination of postoperative specimens from our collected cohort confirmed the close association of upregulated SLC14A1 with metachronous liver metastasis and poor prognosis in patients." (PMID 39061061, 2024). "This study aims to elucidate the role of Solute Carrier Family 14 Member 1 (SLC14A1) in the pathogenesis and progression of CRC metachronous liver metastasis." (PMID 39061061, 2024).
progressive supranuclear palsy (1 paper, 2023). A rare late-onset neurodegenerative disease characterized by supranuclear gaze palsy, postural instability, progressive rigidity, and mild dementia. "SLC14A1 is found to be a diagnostic marker in patients with Progressive Supranuclear Palsy (PSP) in studies of neurological diseases." (PMID 37065902, 2023).
prostate tumor (1 paper, 2016). "mRNA levels of FLRT3 and SLC14A1 also showed a stepwise reduction from benign to primary prostate tumor and metastatic samples in other clinical prostate datasets." (PMID 27732966, 2016).
renal carcinoma (1 paper, 2025). A carcinoma arising from the epithelium of the renal parenchyma or the renal pelvis. "Upregulation of SLC14A1 suppressed the proliferation, migration, and metastatic dissemination of renal carcinoma cells, highlighting its critical role in renal cancer progression and potential as a novel biomarker." (PMID 41301792, 2025). "SLC14A1 was reported to be expressed at a low level in almost every type of renal cancer tissues." (PMID 41301792, 2025).
scrapie (1 paper, 2010). A fatal disease of the nervous system in sheep and goats, characterized by pruritus, debility, and locomotor incoordination. "Comparing the prp2 morphant with the mouse scrapie model revealed 5 genes in common: GFAP, CD9 antigen (CD9), solute carrier family 14 member 1 (SLC14A1), heat shock 22kDa protein 8 (HSPB8) and syndecan 4 (SDC4)." (PMID 21042590, 2010).